SIX2 (SIX homeobox 2)
Diseases named in the same sentence as SIX2 in open-access papers (continued):
Sharing a sentence is not in itself a finding about the gene and the disease.
hearing loss (1 paper, 2021). "Mutations in human SIX1 and SIX2 have been associated with multiple congenital disorders such as branchio-oto-renal syndrome (BOR), renal dysplasia, hearing loss, and frontonasal dysplasia syndrome." (PMID 34490256, 2021). "Independent of BOR, dominantly inherited hearing loss has been associated with mutations in both SIX1 and SIX2." (PMID 34490256, 2021).
Hodgkins lymphoma (1 paper, 2021). A heterogeneous group of malignant lymphoid neoplasms of B-cell origin characterized histologically by the presence of Hodgkin and Reed-Sternberg (HRS) cells in the vast majority of cases. "GATA2 is suppressed by SIX1 and SIX2 during erythropoiesis but activated by SIX1 in Hodgkin lymphoma." (PMID 34768865, 2021).
Hypercalcemia (1 paper, 2023). An abnormally increased calcium concentration in the blood. "Similar to Six2-Cre;Sik1fl/+;Sik2fl/fl;Sik3fl/fl mice, only Six2-Cre;Sik2fl/fl;Sik3fl/fl mice showed increased Cyp27b1 expression and serum 1,25-vitamin D levels, mild (but statistically significant) hypercalcemia, and PTH suppression." (PMID 36862513, 2023).
Kidney Cyst (1 paper, 2012). Abnormal fluid filled sac within the kidney, either acquired or congenital. "Wnt9b transgene activation in Six2-positive cells causes kidney cysts and a transformation of the distal stomach regions into proximal stomach fate." (PMID 22912798, 2012). "Persistent expression of Wnt9b in Six2-positive cells leads to kidney cysts and severe organ failure." (PMID 22912798, 2012). "Although kidney cysts were not present until after birth, upregulation of canonical Wnt signaling was apparent at E12.5 when Six2-cre is initially expressed." (PMID 22912798, 2012).
lung squamous cell carcinoma (1 paper, 2016). "Subgroup analysis of lung squamous cell carcinoma (SQC) showed no significance in SIX2 and SIX3." (PMID 27821176, 2016).
lymphoma (1 paper, 2020). A malignant (clonal) proliferation of B- lymphocytes or T- lymphocytes which involves the lymph nodes, bone marrow and/or extranodal sites. "SIX2 and EIF4E2 AAbs were further validated in independent cohorts of 17 NSCLC and 43 lymphoma patients, respectively, using ELISA." (PMID 32483460, 2020).
microtia (1 paper, 2024). "In the syndromic microtia group, the most common genes were TCOF1 (43.75%; 28 out of 64 cases), SIX2 (4.69%), and HSPA9 in (4.69%) patients." (PMID 38594752, 2024). "As reported in this review, the major gene disorder related to microtia phenotype is found in TCOF1 (32.82%; 28 cases), followed by GSC exon 2 (6.82%), FANCB (4.55%), SIX2 (3.41%), HSPA9 (3.41%) and CDT1 (3.41%) with each characteristic." (PMID 38594752, 2024). "We found 88 cases of genetic data related to microtia, including TCOF1 (31.82%), GSC exon 2 (6.82%), FANCB (4.55%), SIX2 (3.41%), HSPA9 (3.41%), and CDT1 (3.41%)." (PMID 38594752, 2024). "Based on our findings, 64 cases (72.72%) were syndromic microtia [TCOF1 (43.75%), SIX2 (4.69%), and HSPA9 (4.69%)] and 24 cases (27.27%) were non-syndromic microtia [GSC exon 2 (25%), FANCB (16.67%), HOXA2 (8.33%), GSC exon 3 (8.33%), MARS1 (8.33%), CDT1 (8.33%)]." (PMID 38594752, 2024). "In the syndromic microtia group, the most common genes were TCOF1 (43.75%), SIX2 (4.69%), and HSPA9 (4.69%), while in the non-syndromic microtia group, the most frequently found gene was GSC exon 2 (25%), FANCB (16.67%), HOXA2 (8.33%), GSC exon 3 (8.33%), MARS1 (8.33%), and CDT1 (8.33%)." (PMID 38594752, 2024).
renal dysplasia (1 paper, 2021). Renal dysplasia is a form of renal malformation in which the kidney(s) are present but their development is abnormal and incomplete. "Recently, several genetic mutations, mainly associated with Six2, Wnt, Bmp7, and Hnf1β, and copy number variations have been identified in patients with renal dysplasia." (PMID 34395519, 2021).
Renal neoplasm (1 paper, 2018). The presence of a neoplasm of the kidney. "SIX2 is activated in renal neoplasms and influences cellular proliferation and migration." (PMID 30466390, 2018).
thyroid cancer (1 paper, 2020). "We detect a number of recurrent fusions, such as those involving ANO3, RGS9, FUT5, CHI3L1, OR1D4, and LIPG in breast; IGF2 in colon; ETV1 in prostate; and IGF2BP3 and SIX2 in thyroid cancers." (PMID 32631391, 2020). "Although its role in thyroid cancer is unknown, it is noteworthy that THADA-IGF2BP3UIB consistently activates not only IGF2BP3 but also SIX2." (PMID 32631391, 2020).
type 2 diabetes (1 paper, 2026). "Downregulation of SIX2 and SIX3 alters gene regulatory programs associated with β-cell homeostasis and contributes to type 2 diabetes." (PMID 41892811, 2026).
tumor (24 papers, 2013 to 2025). "In this study, relapse-associated Scissor+ tumor cells were consistent with previous studies, showing significant upregulation of CSC markers SIX2, PROM1, and NCAM1." (PMID 40098972, 2025). "While SIX2+CITED1+ WT progenitor cells have been demonstrated to drive tumor initiation, the molecular triggers enabling their survival and immune evasion within the immunocompetent microenvironment of WT remain elusive." (PMID 40534868, 2025). "Four primary cell populations were first identified using canonical cell markers: WT tumor cells (WT1, NCAM1, SIX1, SIX2, PAX2), cancer-associated fibroblasts (CAFs) (ACTA2, TAGLN, COL1A1, PDGFRB), endothelial cells (PECAM1, CLDN5, ENG, VWF) and immune cells." (PMID 40098972, 2025). "Six1 and Six2 are homologous typing transcription regulators, which can affect and regulate the downstream gene expression related to tumor cell migration and proliferation through a variety of signaling pathways." (PMID 36062065, 2022). "In this respect, it has been shown that PPARɣ inhibits SIX2 activity and induces tumor cell apoptosis or may promote tumor cell development in renal cancer." (PMID 40227577, 2025). "Of the predicted other drivers, SIX2 regulates BC metastasis by downregulating E-Cadherin, and KD of SIX2 decreases distant metastasis without affecting primary tumor growth or the associated (lymph)angiogenesis." (PMID 39696035, 2024). "scRNA‐seq data revealed a strong overlap between the tumor of origin and the SIX2+CITED1+ cells." (PMID 37114795, 2023). "To decipher the renal commitment signature of the SIX2+CITED1+ cells, we perform trajectory analysis on the SIX2+CITED1+ cells together with the tumor from which they were originally selected (WT total, WT‐TOT) and the xenograft that they generated in vivo, identifying 3 distinct states." (PMID 37114795, 2023). "In WT, nephrogenic progenitor cells co-expressing SIX2 and CITED1 have been identified as tumor-initiating cells, capable of recapitulating tumorigenesis in xenotransplantation models." (PMID 40534868, 2025). "The results revealed that tumor cells exhibited significantly elevated expression levels of WT1, SIX1, SIX2, and CITED1, supporting the accurate annotation of tumor cells." (PMID 40534868, 2025). "Previous studies have identified SIX2+CITED1+, PROM1+ or NCAM1+ALDH1+ tumor cells as potential CSC-like populations in WT." (PMID 40098972, 2025). "Therefore, the potential anti-tumor effect of LiCl depends on its dose; low concentrations of LiCl induce proliferation via upregulating Six2 expression, while high LiCl concentration decreases both proliferation and Six2 expression, which is connected to the Wnt/β-catenin signaling pathway." (PMID 36836894, 2023). "qRT-PCR analysis for human transcript levels showed significant elevation of renal “stemness” and progenitor genes that mark the early renal lineage, including SIX2 and OSR1, compared to their primary tumour of origin." (PMID 23239665, 2013). "Specifically, the role of key nephron progenitor transcription factors, such as SIX2, in modulating EGFR expression, and whether intervening in this regulatory pathway could inhibit tumor progression and recurrence, warrants deeper exploration." (PMID 40098972, 2025). "Integration of scRNA‐seq data (GSE175698) showed distinct differences in gene expression between SIX2+CITED1+ cells from hFK and WT, WT xenografts and the tumor of origin (WT‐TOT); similarities between WT SIX2+CITED1+ cells and their tumor of origin (WT‐TOT) are evident." (PMID 37114795, 2023). "Two tumours with MLLT1 mutations also had CTNNB1 mutations; no MLLT1-mutant tumours had accompanying WT1, WTX, DROSHA, DGCR8, SIX1, or SIX2 mutations." (PMID 26635203, 2015). "Therefore, the potential of SIX2 in other tumor EMT is obvious, but its role in the CRC is not yet clear." (PMID 34526059, 2021).
tumor (continued). "In tumorigenesis, NCAM1+CD133−marks SIX2+ blastema that includes the ALDH1+ WTcancer stem/initiating cells, while NCAM1+CD133+ andNCAM1−CD133+ specifying early and lateepithelial differentiation, are severely restricted in tumor initiation capacity andtumor self-renewal." (PMID 27020553, 2016).
cancer (15 papers, 2016 to 2025). A tumor composed of atypical neoplastic, often pleomorphic cells that invade other tissues. "Moreover, five genes, including CITED2, C8orf44‐SGK3, FUZ, P2RY1, and SIX2, were associated with carcinoma migration." (PMID 38363001, 2024). "The transcriptional regulator Sox2 has been shown to be directly regulated in developmental and cancer contexts by Six1, Six2, Six3, and Six6 to further promote stem/progenitor cell phenotypes." (PMID 34490256, 2021). "Increased expression of either SIX1 or SIX2 in several cancer types reduced the level of CDH1 through either activating known repressors of CDH1, such as Zeb proteins, or by CDH1 promoter methylation." (PMID 34490256, 2021). "The so subfamily (SIX1 and SIX2), particularly SIX1, have been frequently implicated in the promotion, invasion, and survival of a variety of cancers." (PMID 34490256, 2021). "We demonstrated that SIX2+CITED1+ cells from WT exhibited nephrogenic cancer stem cell (CSC) traits and, upon transplantation into NOD/SCID mice, formed consecutive xenografts with histological features similar to the WT of origin, as well as metastatic capabilities." (PMID 37114795, 2023). "As one might predict, increased levels of SIX2 are highly correlated with cancers involving the kidney." (PMID 34490256, 2021). "It is also unclear whether any of the identified transcription factor binding sites upstream of Six2 or other SIX family members become re-engaged in cancer." (PMID 34490256, 2021). "In addition to the four genes (Fos, Col1a1, Trim63, and Six2), our study identified other potential molecular factors of high-intensity aerobic exercise, which may prevent cancer proliferation." (PMID 35801156, 2022). "Despite these limitations, our study clearly suggests that the high-intensity aerobic exercise resulted in changes in the expression of muscle-derived anticancer genes (Fos, Col1a1, Trim63, and Six2) that may account for the cancer-preventive effect of aerobic exercise." (PMID 35801156, 2022). "Cells expressing SIX2 and CITED1 fulfill cancer stem cell criteria by reliably recapitulating WT in transplantation studies." (PMID 37114795, 2023). "Notably, among the 14 TFs whose binding sites were sex-dependently enriched across different cancers, eight were previously found to be enriched among sex-biased expressed genes, including SP1, ETV1, ELF1, E2F1, CREB1, CTCF, SIX2, and SOX2." (PMID 39716176, 2024). "Of the genes that were altered in all cancer subtypes, the expression of five matched all datasets (HOXC8, HOXC11, HOXD8, PROX1, SIX2), although the overlap was found when considering the expression in the majority of the subtypes as HOXC11 and PROX1 were downregulated in TN CSC." (PMID 28202042, 2017).
kidney disease (1 paper, 2022). "Although we have not observed a spontaneous kidney disease phenotype in mice that lack 1 copy of Qpc in SIX2-derived kidney epithelial cells, it plausible that Six2-Qpc+/− heterozygotes might be more susceptible to kidney injury." (PMID 35341793, 2022).
SIX2 also shares sentences with these, for which no sentence is quoted: hepatocellular carcinoma (2 papers); infection (2); lung carcinoma (2); acute T-cell leukemia (1); breast tumor (1); chondrosarcoma (1); chronic renal failure (1); clear cell renal cell cancer (1); congenital heart disease (1); cystic kidneys (1); Hypertension (1); Lowe Syndrome (1); lung adenocarcinoma (1); mesangial sclerosis (1); Parkinson disease (1); ptosis (1); triple-negative breast carcinoma (1).